IL1B (interleukin 1 beta)
Diseases named in the same sentence as IL1B in open-access papers (continued):
Sharing a sentence is not in itself a finding about the gene and the disease.
metabolic syndrome (continued). "It is interesting to note that certain factors related to inflammation and metabolic syndrome, namely IL-1β and serum triglycerides, remained significantly different between WT and fat-1 mice following the antibiotic treatment and co-housing experiments." (PMID 26062993, 2015). "The key results presented here demonstrate that the macrophage-derived inflammatory mediator IL-1β potentiates the hepatic manifestation of the metabolic syndrome by stimulating lipogenesis and hepatic steatosis in obese mice." (PMID 25216251, 2014). "Gene expression of IL-1β in periodontal tissues was also higher in the dyslipidemia group than that in the control group (p < 0.05)." (PMID 23295061, 2013). "This metabolic endotoxemia is considered a key inducer of metabolic syndrome, with multiple cytokines (Tnfα and IL-1β) and chemokines (e.g. Mcp-1) contributing to the progression of both alcoholic-liver disease (ALD) and NAFLD." (PMID 23409132, 2013). "Subsequently, Caspase-1 inhibition by quercetin and allopurinol prevented kidney IL-1β and IL-18 release and over-production triggered by hyperuricemia and dyslipidemia in this model." (PMID 22701621, 2012). "In turn, both IL-6 and IL-1β act on the liver to produce a characteristic dyslipidemia in metabolic syndrome, one which manifests as increased very low density lipoprotein (VLDL) and decreased high density lipoprotein (HDL)." (PMID 22369568, 2011). "The mechanisms underlying the correlation between dyslipidemia and low testosterone levels may involve proinflammatory substances (e.g., TNF-α, IL-8, IL-6, and IL1β)." (PMID 40489567, 2025). "Similarly, a significant increase in the mRNA expression levels of NF‐κB, IκBα, TNF‐α, IL‐1β, and IL‐6 was observed in the hypothalamus of metabolic syndrome mice." (PMID 40708775, 2025). "This dyslipidemia seems to activate IL-1β production in the cardiomyocytes." (PMID 40672362, 2025). "Like IL-10’s implications in metabolic syndrome, IL-1β plays a role in this intricate scenario." (PMID 38674931, 2024). "The findings at the 8-week revealed that the microbiota from the cohort with knee OA and metabolic syndrome correlated with elevated levels of systemic inflammatory biomarkers, such as IL-1β and IL-6, alongside heightened intestinal permeability and exacerbated OA symptoms." (PMID 39656496, 2024). "Moreover, the role of recent biomarkers including NLRP3 inflammasome and its downstream cytokines including IL-1β in the pathogenesis of metabolic syndrome as well as its comorbid diseases are warranted." (PMID 38846018, 2024). "In particular, treatment with risperidone, as the least atypical antipsychotic, led to an increase in pro-inflammatory IFN-α2, IL-1β, and IL-7 in schizophrenia patients with metabolic syndrome and was ineffective in lowering pro-inflammatory cytokines in patients without it." (PMID 37239308, 2023). "Accordingly, we previously showed that ex vivo treatment for 2 h with H2O2 (produced with glucose oxidase) in PBMCs from patients with metabolic syndrome to mimic chronic stress caused a transient inflammatory response with an increase in the production of IL6, IL8, and IL1β." (PMID 34065281, 2021). "Interestingly, decreases in MFN-1 and MFN-2 in the brain were reported in a mouse model of metabolic syndrome that presented microglial activation and increased IL-1β expression." (PMID 33612100, 2021). "It is hypothesized that increasing serum fatty acids associated with metabolic syndrome stimulate TLR4 leading to increased serum levels of TNF-alpha, IL-1B, and IL-6." (PMID 33072103, 2020). "Furthermore, patients with SS who also have metabolic syndrome have increased serum levels of leptin and IL-1β." (PMID 32370746, 2020).
metabolic syndrome (continued). "The increasing trend of IL-6 and Il-1β can be explained by antipsychotics (especially atypical antipsychotics) side effects such as metabolic syndrome in the long period, as increased levels of IL-6, IL-1β, TNF-α, IL-2, IFN-γ, and IL-4 have been reported in patients with metabolic syndrome." (PMID 31908647, 2019). "Notably, salivary cytokines—such as interleukin-6 (IL-6), tumor necrosis factor-alpha (TNF-α), and interleukin-1β (IL-1β)—can be co-analyzed with SAA to assess inflammatory states associated with chronic stress, metabolic syndrome, or low-grade systemic inflammation." (PMID 40806495, 2025). "The cytokines and chemokines produced in the lesions reach the blood, so the patient may suffer from comorbidities, especially IL-1β and TNF-α causing cardiovascular complications, metabolic syndromes (such as obesity, dyslipidemia, atherosclerosis, and type 2 diabetes), and autoimmune diseases." (PMID 39513038, 2024). "In an STZ-induced rat model of diabetic nephropathy (DN) with hyperuricemia and dyslipidemia, overexpression of NLRP3 inflammasome components [apoptosis-associated speck-like protein (ASC) and caspase-1] has been found to be associated with elevated IL-1β and IL-18 levels." (PMID 34267672, 2021). "Therefore, the observed elevated level of inflammatory cytokine IL-1β and the decreased level of transporters/aquaporins may be beneficial to dyslipidemia-induced renal alterations." (PMID 32929357, 2020). "Our finding that obese individuals who have met the diagnostic criteria for metabolic syndrome had higher mean levels of IL-1β, IL-6, and IL-15 in VAT than obese individuals without MS also supports this hypothesis." (PMID 26516848, 2015). "It has indeed been demonstrated in numerous studies that HS and metabolic syndrome (MetS) share a core link through meta-inflammation, driven by common pro-inflammatory cytokines, such as tumor necrosis factor (TNF)-α, interleukin (IL)-1β and IL-6." (PMID 42266681, 2026). "Raising IL-1β, NF-kβ signaling, insulin, insulin resistance, FFAs, MGO, and AGEs leads to dyslipidemia and vascular complications." (PMID 39877627, 2025). "Özlem Fentoğlu found significant correlations between serum and gingival crevicular fluid cytokines (IL-1β and TNF-α) and the TC/HDL ratio in patients with dyslipidemia." (PMID 38684998, 2024). "LPS, ROS, MDA, and Keap1 were significantly positively correlated with inflammatory cytokines (IL-1β, COX2, TNF-α, IL-6, and iNOS), metabolic syndrome (LDL-C, T-CHO, TG, and BUN), ABW, and ADG at 45 d, 60 d, and 90 d of sample collection." (PMID 38003191, 2023). "Pro-inflammatory cytokines, such as IL-1β, IL-6, and TNF-α, are produced in adipose tissues during pathogenesis of metabolic syndrome." (PMID 36826001, 2023). "IL1β, IL6 and TNFa are highly expressed in metabolic syndrome, and their expression levels are down-regulated after exercise." (PMID 37053002, 2023). "EPE attenuated dyslipidemia, serum transaminases, tumor necrosis factor (TNF)-α, interleukin (IL)-1β and liver lipid accumulation, nuclear factor (NF)-κB p65, and lipid peroxidation, nitric oxide and enhanced antioxidants." (PMID 37397470, 2023). "In a model of dyslipidemia induced by a high-fat diet in rats, BCP treatment resulted in reduced TNF and IL-1β levels in the aorta." (PMID 37891972, 2023). "According to our findings, the AZGP1 gene-enriched pathway in the skeletal muscle is directly related to dyslipidemia, inflammatory response mediated by TNF-alpha and IL-1b, and metabolic diseases." (PMID 35804531, 2022). "In metabolic syndrome, MCP-1, IL-18, and IL-1B are elevated and stimulate pro-inflammatory actions of tissue neutrophils and macrophages in vascular endothelial and smooth muscle cells." (PMID 36012132, 2022).
metabolic syndrome (continued). "In this study, the levels of the activators of the NF-Kβ signaling pathway including FFAs, g-Alb, MGO, AGEs, IL-1β, glycated and oxidized LDL, as well as expression of Nf-kβ were higher in the metabolic syndrome group than in the normal group." (PMID 33995940, 2021). "Moreover, given the benefits of canakinumab seen in the CANTOS trial, along with the present findings, IL-1β blocker and 1α,25(OH)2D3 might complete each other to attenuate metaflammation in adipose tissue, thus to potentially help prevent metabolic syndrome and subsequent cardiovascular disease." (PMID 30697360, 2019). "Then, a reduction in IL-6 and IL-1β, but not in TNF-α, was observed after 8 weeks of consuming 75 g/day of whole grain products among overweight/obese individuals at risk of metabolic syndrome." (PMID 40944222, 2025). "Rats with dyslipidemia (D group) presented higher tissue levels of evaluated cytokines compared to the C group (p ≤ 0.020), but when compared to the H group, IL-1β, and IL-6 were not significantly different (p > 0.25)." (PMID 35163364, 2022). "Studies have shown that IL-1β levels are elevated in non-diabetic offspring of diabetics and correlate with metabolic syndrome, as well as increased expression of both IL-1β and its receptor in visceral adipose tissue in obese individuals." (PMID 35625904, 2022). "The results have suggested that GXNT could regulate dyslipidemia, improve heart function, and inhibit the levels of ox-LDL, CRP, TNF-α, IL-1β, SOD, MDA, vWF, and ET-1, as well as platelet aggregation." (PMID 35935588, 2022). "In these ADPKD patients with metabolic syndrome, IL-1β plasma protein was significantly higher compared to non-ADPKD, non-diabetic patients with comparable renal function." (PMID 35204131, 2022). "PLWHA with metabolic syndrome had higher percentages of IL-1β+ monocytes after oxLDL stimulation (p = 0.018) as compared to PLWHA without metabolic syndrome." (PMID 33028018, 2020). "Therefore, we have decided to search for the relationship between the TNFα gene polymorphisms and serum levels of proinflammatory cytokines (IL-1α, IL-1β, IL-6, TNFα, IFNγ) and CRP in women with metabolic syndrome." (PMID 30383538, 2018). "Concurring with this notion, restoration of the HDL concentration until reaching the levels found in healthy subjects without metabolic syndrome was able to diminish the LPS-stimulated IL-1β production in cultured primary human monocytes in vitro." (PMID 29850624, 2018). "Metabolic syndrome patients with hypertriglyceridemia exhibited a nonsignificant increase in serum IL-1β as compared to metabolic syndrome patients without abnormally high triglyceride values." (PMID 29850624, 2018). "The median concentration of IL-1β and TNFα in patients with metabolic syndrome was elevated when compared with patients without metabolic alterations." (PMID 26101459, 2015). "The aim of this study is to establish interactions between the GLP-1 plasma levels and metabolic syndrome clusters and adipokines profile (leptin, adiponectin, resistin) and proinflammatory cytokines (TNFα, IL-6, IL1β, IL-17) in diabetic subjects with or without MAFLD." (PMID 41683648, 2026). "While no significant impact was observed on IL-1β levels, these findings suggest that berberine might be particularly useful in managing metabolic syndrome, especially in specific populations such as the Chinese." (PMID 40006007, 2025). "Furthermore, IL-1β concentrations did not correlate significantly with clinical parameters of metabolic syndrome, except for insulin sensitivity/resistance (insulin level and HOMA-IR index)." (PMID 37703108, 2023). "Furthermore, SS patients with metabolic syndrome have increased serum levels of leptin and interleukin (IL)-1β compared to those without metabolic syndrome." (PMID 32370746, 2020).
metabolic syndrome (continued). "Notably, IL-1β, but not IL-18, participates in the development of metabolic syndromes by inhibiting adipocyte differentiation that is required for the maintenance of insulin sensitivity and inducing inflammation." (PMID 30717382, 2019). "It is therefore important to determine whether IL-6 or IL-1β mediates adipose tissue metaflammation during macrophage infiltration via modulating MAPK or NF-κB pathway, to help further elucidate the pathophysiology of metabolic syndrome." (PMID 30697360, 2019). "The idea that both nonclassical monocytes and IL-1β may exert their prominent inflammatory actions in metabolic syndrome patients is congruent with numerous works showing that systemic inflammation is linked to the pathogenesis of metabolic dysfunction." (PMID 29850624, 2018). "Additionally, obese individuals with metabolic syndrome had higher IL-1β levels in VAT than did obese individuals without this syndrome (p = 0.003)." (PMID 26516848, 2015). "However, IL-1β was only measured in serum samples and direct evidence regarding the role of nonclassical monocytes in IL-1β production in metabolic syndrome patients remains to be further elucidated; therefore, discussion of these results makes no attempt to conjecture beyond that." (PMID 29850624, 2018). "However, to the best of our knowledge this is the first report suggesting that nonclassical monocytes could be a main cellular source of IL-1β in subjects with metabolic syndrome that show low HDL levels." (PMID 29850624, 2018). "After more than two years of follow-up, it was shown that MTX did not produce lower levels of IL-1β, IL-6, CRP, or components of the metabolic syndrome than the placebo." (PMID 41155215, 2025). "When the obese study participants were stratified according to the presence or absence of metabolic syndrome (MS), we found that individuals diagnosed with MS had significantly higher VAT levels of IL-1β (0.88 vs. 0.29 ng per 1 mg of total protein, p = 0.003)." (PMID 26516848, 2015). "Thus, present data suggest a direct relationship among increased percentage of nonclassical monocytes, elevated concentrations of IL-1β, and low HDL levels in patients with metabolic syndrome." (PMID 29850624, 2018).
heart failure (179 papers, 2007 to 2026). Inability of the heart to pump blood at an adequate rate to meet tissue metabolic requirements. "Specifically, the inflammatory markers hs-CRP, IL-1β, and IL-6 were significantly positively correlated, suggesting that these markers jointly participate in the inflammatory response associated with heart failure." (PMID 41333015, 2025). "MCC950 was also able to repress IL1B expression in white adipose tissue and subsequent insulin resistance, as well as prevent heart failure in TET-2 deficient mouse models." (PMID 39988580, 2025). "Some biomarkers, such as CRP, IL-6, and IL-1β, related to aging or diseases, such as heart failure and cancer, are associated with MCI." (PMID 40281902, 2025). "Inhibition of IL-1β has been demonstrated to be associated with improvement in LV strain and reduction in heart failure hospitalisation." (PMID 38997620, 2024). "We observed that a variety of genes upregulated in ACM cardiac myocytes were downregulated following anti-IL-1β antibody treatment, including major heart failure and inflammation associated genes (highlighted in red)." (PMID 39763850, 2024). "Supporting thisdata, a high expression of cytokines such as tumor necrosis factor-alpha (TNF-α),caspase-9, interleukins 1 beta (IL-1β), and IL-6 in the heart and serum of LVADcandidates are associated with the severity of heart failure." (PMID 39484122, 2024). "DNMT3A mutated monocytes from patients with heart failure have been shown to express higher mRNA levels of IL-1β, IL-6 and IL-8, macrophage inflammatory chemokines CCL3 and CCL4 and the inflammasome NLRP3." (PMID 36835370, 2023). "In a murine heart failure model, Tet2 deficiency negatively affected cardiac remodeling and increased pro-inflammatory interleukin (IL)-1β." (PMID 36835370, 2023). "High plasma levels of Stromal Cell-Derived Factor 1 (SDF-1), IL-1β and IL-6 were associated to cardiac inflammation, heart failure and cardiovascular mortality." (PMID 36158826, 2022). "IL-1β is a crucial cytokine promoting the inflammatory reaction in heart failure, Tet2 mutation in blood cells can increase atherosclerotic plaque size due to elevated IL-1β signaling in mice." (PMID 36189207, 2022). "Several pro-inflammatory cytokines, including tumor necrosis factor-alpha (TNF-alpha), interferon-gamma, interleukin-1-beta, interleukin-6, interleukin-17, and interleukin-18 have been implicated in the pathogenesis of heart failure." (PMID 33391898, 2021). "The levels of inflammatory factors IL-6 and IL-1β are positively associated with heart failure severity." (PMID 34658880, 2021). "Depletion of Tet2 in blood cells was shown to worsen cardiac remodeling and function in two experimental murine models of heart failure, implicating a causative role of Il-1β overproduction in this process." (PMID 33114351, 2020). "An IL-1β-independent role for caspase-1 in cardiomyocyte cell death and heart failure has emerged but the mechanisms underlying these effects are incompletely understood." (PMID 25501827, 2014). "SN excitability activates the NLRP3 vesicles in the heart and generates IL-1β to induce myocardial injury, and recent studies have also demonstrated that cardiac insufficiency occurring after MCAO in mice is associated with sustained pro-inflammatory changes in monocytes/macrophages driven by IL-1β." (PMID 41143181, 2025). "Mechanistic studies suggest that IL-1β signaling and pyroptosis are critical in exacerbating initial ischemic injury, resulting in increased infarct size and reduced cardiac contractility, thereby elevating the risk of heart failure (HF)." (PMID 39811465, 2025). "In addition, proinflammatory cytokines (TNF-α, IL-1β, etc.)produced by adipose tissue have been associated with a poor prognosis of heart failure." (PMID 40507126, 2025). "The increase in IL-1β and other inflammasome proteins may cause heart failure via inflammation of the ventricles." (PMID 38660388, 2024).